MTOR (mechanistic target of rapamycin kinase)
Diseases named in the same sentence as MTOR in open-access papers (continued):
Sharing a sentence is not in itself a finding about the gene and the disease.
glioma (continued). "In this study, the assessment of the autophagic process using different methodological approaches has suggested that the presence of WNK2 inhibits the autophagic flux in glioma cell lines and it is independent of the mTOR pathway." (PMID 32093151, 2020). "Furthermore, Hagerstrand and colleagues demonstrated that glioma cells showed ligand-independent AKT phosphorylation and that combined inhibition of IGF-IR and PI3K or mTOR reduces cell viability." (PMID 33604294, 2020). "As hypoxia worsens, hypoxia-induced glioma-derived exosomal miRNA-199a-3p can be upregulated by the activation of HIF-1α and is able to increase the ischemic injury of neurons by inhibiting the mTOR pathway." (PMID 33110474, 2020). "In this study, we found that bortezomib could significantly inhibit the proliferation of glioma cells using MTT assay and further found that this effect was mediated by the PTEN/PI3K/AKT/mTOR signalling pathway." (PMID 32126150, 2020). "Finally, we showed that inhibition of mTOR with rapamycin blocked the effects of JMJD2A on protein synthesis, cell proliferation and colony formation of glioma cells." (PMID 32256210, 2020). "Knockdown of LINC00998 enables glioma cells to acquire high proliferation ability by regulating CBX3 and the c-Met/Akt/mTOR signaling pathway, which indicates that LINC00998 may provide a rationale for precision therapy in glioma patients." (PMID 33268783, 2020). "Also, depletion of Mcl-1 by mTOR inhibitors increase vulnerability to PARP inhibitors, providing additional therapeutic options for glioma." (PMID 33747896, 2020). "Besides, upon the treatment of inhibitors for c-Met and mTOR (SU11274 and rapamycin), glioma cells (A172, U251, and U373) exhibited a similar effect as cells treated by LINC00998." (PMID 33268783, 2020). "Inhibition of mTOR with rapamycin blocked the effects of JMJD2A on protein synthesis, cell proliferation, and colony formation, indicating that the mTOR pathway is important for the role of JMJD2A in glioma." (PMID 32256210, 2020). "Additionally, the clinical dual PI3K/mTOR inhibitor NVP-BEZ235 cooperated with the autophagy inhibitor CQ and led to apoptosis in PTEN-mutant glioma xenografts in vivo." (PMID 33123479, 2020). "These gliomas displayed sensitivity to voxtalisib, the dual PI3K/mTOR inhibitor." (PMID 31817676, 2019). "In human glioma, simultaneous activation of multiple RTKs, including EGFR, VEGFR, FGFR and PDGFR, can constitutively activate key oncogenic downstream cascades, including PI3K-Akt-mTOR and Erk-MAPK signaling." (PMID 31794427, 2019). "Herein, the results of this study suggested that Prucalopride inhibited glioma cells proliferation and migration as well as induced apoptosis and autophagy, which was probably modulated by suppression of protein kinase B (AKT)- mammalian target of rapamycin (mTOR) signaling." (PMID 29866060, 2018). "The levels of PI3K/mTOR signaling proteins, including pAkt, pS6 and P4EBP1 decreased in a dose- and time-dependent manner in all tested glioma cells as well as in the glioma tumor-initiating cell line GSC11." (PMID 28423515, 2017). "Therefore, it is likely that a difference between the activity of these mTOR inhibitors exists in RPE cells, in contrast to glioma cells, where it was demonstrated that they all induce autophagy to a similar extent." (PMID 28353645, 2017). "Additionally, a combination of a dual PI3K and mTOR inhibitor, NVPBEZ235, with CQ induced apoptosis of glioma cells." (PMID 28716053, 2017). "Additionally, metformin has been shown to suppress mTOR activity through the upregulation of key components of the mTORC1 complex, PRAS40 and RAPTOR, in glioma cell and animal models." (PMID 28193239, 2017).
glioma (continued). "mTOR incorporates oncogenic signaling from some growth factor receptors via PI3K, to modulate nutrient status and cellular energy, to stimulate downstream targets that promote tumor growth and suppress glioma cell invasion." (PMID 27329594, 2016). "Lastly, considering that low grade gliomas have a propensity to be driven to a more aggressive phenotype through signaling from the microenvironment, TEM and other mTOR inhibitors can be explored in combination with other drugs for better and effective treatment regime in such tumors." (PMID 26940200, 2016). "Amounts of phosphorylated and non-phosphorylated Akt and mTOR in glioma tissues were analyzed to determine the possible mechanisms of honokiol-induced autophagy." (PMID 27774504, 2016). "Hono treatment blocks the phosphoinositide 3-kinase (PI3K)/mammalian target of rapamycin (mTOR) pathway-mediated immunoresistance of glioma without inhibiting critical proinflammatory T cell functions." (PMID 27074557, 2016). "An intracranial model was established to test the effects of HNK on induction of autophagy in development of glioma by analyses of phosphorylated (p) and non-phosphorylated Akt and mTOR." (PMID 27774504, 2016). "In glioma cells, the function of GOLPH3 requires mTOR and its effector YB-1." (PMID 28983350, 2015). "Our data provide evidence that the PI3K/mTOR/S6 signaling pathway can be activated through expression of EGFR/PI3K p110α rather than through reduced expression of PTEN in glioma." (PMID 24718026, 2014). "In gliomas, the PI3K/PKB/mTOR and the MAPK/ERK pathways are hyper-activated by specific mutations." (PMID 23451269, 2013). "Whether resistance to BRAF V600E inhibitors also arises in gliomas, where EGFR and PI3K/mTOR pathways are often over-activated, remains to be seen in neuro-oncology patients treated with BRAF V600E inhibitors." (PMID 23717811, 2013). "Our data agrees with recent studies in EGFR driven gliomas models that show mTOR can be regulated by the PKC pathway independent of Akt phosphorylation." (PMID 21267448, 2011). "As Iridals interacts with PKCα and RasGRP3-molecules that regulate Akt and STAT3 signaling, and since inhibition of Akt/mTOR and STAT3 signaling are being targeted for GBM treatment we evaluated the effect of Iripallidal on glioma cell proliferation and these signaling pathways." (PMID 20576128, 2010). "Interestingly, previous studies have not demonstrated elevated expression of mTOR in canine glioma cell lines." (PMID 42135822, 2025). "Additionally, Sch B regulates the HOTAIR-miR-125a-mTOR pathway by reducing hox transcript antisense intergenic RNA (HOTAIR) expression and increasing miR-125a-5p expression to exert its function in suppressing the migration and invasion of glioma cell lines." (PMID 39995410, 2025). "Building on these findings mTOR inhibitors may offer a novel therapeutic avenue in glioma—not solely for tumor suppression, but for mitigating the tumor-induced neurological dysfunction seen consistently in both preclinical models and in clinical care." (PMID 41301687, 2025). "Similarly, the negative autophagy regulator mTOR was not significantly differentially expressed between the two glioma grades (p = 0.07), but higher expression was noticed in higher grade." (PMID 38203743, 2024).
glioma (continued). "Furthermore, miR-374a-targeted genes exhibited significant association with pathways such as cancer, Ras signaling, MAPK signaling, PI3K-AKT signaling, Glioblastoma signaling, EGFR tyrosine kinase inhibitor resistance, mTOR signaling, miRs in cardiomyocyte hypertrophy, EGF/EGFR signaling and glioma." (PMID 39348350, 2024). "miR-199 can downregulate the expression of the mTOR signaling pathway to enhance the sensitivity of HCC to DOX.miR-199 also targets the AGAP2 gene and suppresses its expression, enhancing the sensitivity of glioma cells to temozolomide and inhibiting tumor progression." (PMID 39220365, 2024). "Moreover, we further found that phosphorylation of P70S6K also could be detected after treated with the mTOR inhibitor rapamycin in the co-transfection of YANK2 and P70S6K, and the p-p70S6K T389 level in YANK2-positive glioma was also increased by IHC assay." (PMID 38714727, 2024). "Also, LINC00663 was reported to be highly expressed in glioma, and LINC00663 knockdown could restrain cell viability by modulating AKT/mTOR pathway." (PMID 39219375, 2024). "The study identified eCF324 as a potent PI3K/mTOR inhibitor for GB, with EC50 values of 13 nM and 10 nM in U87 and T98 cell lines, respectively, and demonstrated strong synergistic effects with GDC0941, showing superior potency and high specificity for glioma cells." (PMID 39328617, 2024). "Thus, mTOR inhibitors can potentially reduce the hyperactive effects of D2HG and may reduce seizures induced by IDHmut gliomas." (PMID 38026690, 2023). "In gliomas, many cuproptosis‐related genes could activate the androgen receptor, cell cycle, DNA damage response, and PI3K/AKT signaling pathways and inhibit TSC/mTOR and EMT signals." (PMID 37515314, 2023). "Moreover, in glioma cells in hypoxic conditions, an augmentation of the expression of Fat1 induce an increase of HIF-1 expression through growth factor receptors-Akt-mTOR pathway, suggesting that Fat1 controls the invasiveness of glioma cells through HIF-1 signaling." (PMID 35269788, 2022). "Additionally, previous studies have demonstrated that Akt/mammalian target of rapamycin (mTOR) signaling pathway is an essential regulator for NSC proliferation and participates in manipulating redox homeostasis in macrophage and glioma cells." (PMID 35265266, 2022). "For example, inhibiting the expression of uPA/uPAR blocks the invasion of glioma SNB19 cells by reducing Ras mediated phosphorylation of FAK, p38MAPK, c-Jun N-terminal kinase (JNK) and ERK1/2 and MAPK kinase (MEK) activation of the PI3K/AKT/mammalian target of rapamycin (mTOR) signalling pathway." (PMID 35303878, 2022). "We analyzed and summarized signal pathway of the Hippo/YAP, PI3K/AKT/mTOR, miRNA, WNT/β-catenin, Notch, Hedgehog, TGF-β, TCS/mTORC1 signal pathway, JAK/STAT signal pathway, MAPK signaling pathway, the relationship between BBB and signal pathways and the mechanism of key enzymes in glioma." (PMID 35935338, 2022). "In addition, metformin suppressed the proliferation of glioma cells through PRAS40-mediated mTOR inhibition independent of AMPK." (PMID 33578894, 2021). "Studies have shown that MEG3 is under-expressed in gliomas, and its over-expression has a significant inhibitory effect on the proliferation and migration of glioma cells, while promoting its apoptosis and autophagy, and inhibiting the PI3K/AKT/mTOR signalling pathway." (PMID 33499813, 2021).
glioma (continued). "Our current research showed that TSN plays a crucial role in the anti-tumor effect on glioma cells in vivo and in vitro through interference of the proliferation, invasion, migration, apoptosis, and cycle distribution, mediated through the inhibition of the PI3K/Akt/mTOR signaling pathway." (PMID 34530814, 2021). "Another study shows that KIF3C expression in the low-grade glioma tissue is higher in comparison to the high-grade glioma tissue, and patients with high KIF3C expression have a longer survival time; functionally, KIF3C inhibits glioma cells’ growth through modulating the PI3K/Akt/mTOR pathway." (PMID 34193018, 2021). "As research continues, an increasing interest in the function of CRNDE in glioma reveals that CRNDE could modulate glioma cell growth and invasion with EGFR activation and through mTOR signaling, and promote malignant progression by attenuating miR-384/PIWIL4/STAT3 axis in GBM." (PMID 34454479, 2021). "Indeed, this concept was tested in one approach, which combined the lysosomotrophic agent chloroquine (CQ) that blocked the activity of lysosomal proteases, with the PI3K/mTOR/AKT inhibitors (AKT-1/2 and PI-103), resulting in the overall potentiation of glioma cell death." (PMID 32517694, 2020). "Based on the structure activity relationships identified in this study, five new derivatives were synthesized and tested, which exhibited potent activity against glioma cells but not superior to the dual PI3K/mTOR inhibitor and lead compound of the screening eCF324." (PMID 31787462, 2020). "In hypoxic hepatocellular and glioma tumor cells, knocking down lincRNA-p21 could enhance radio-sensitivity through HIF-1/Akt/mTOR/P70S6K signaling, while in human colorectal cancer, lincRNA-p21 enhanced the sensitivity of radiotherapy by targeting the Wnt/β-catenin signaling." (PMID 31748715, 2020). "In other words, activating the mTOR pathway might relieve the hypoxic injury of peritumoral normal neuronal cells induced by glioma cells and might inhibit the invasive growth of glioma cells in a hypoxic microenvironment." (PMID 33110474, 2020). "In addition to endocytic and vesicular compartment GO terms, DGCA GO analysis for positive NTRK2 correlations in glioma reactome pathways revealed enrichment for genes in the PI3K and mTOR signaling pathways, which have been known to regulate cellular proliferation in normal and oncogenic contexts." (PMID 32532995, 2020). "The first solution could consist of changing rapamycin for dual PI3K/mTOR inhibitors like the NVP-BEZ235 which has demonstrated effectiveness in vivo, or mTORC1/mTORC2 inhibitor is AZD2014 which radiosensitizes glioma." (PMID 33718332, 2020). "Furthermore, NVP-BEZ235 (a dual mTOR and PI3K inhibitor currently being tested in clinical trials) induced autophagy in solid tumors, and synergistically acted in combination with CQ through increased apoptosis in glioma cells." (PMID 32517694, 2020). "Therefore, in addition to AKT/mTOR, AMPK might also contribute to SRT2183-induced autophagy in glioma cells." (PMID 31319814, 2019). "Until now, miR-451a was shown to be involved in several cancers, including glioma and gastric cancer, where it acts as a potential tumor suppressor affecting cell proliferation, invasion and apoptosis, perhaps via the regulation of the PI3K/AKT /mTOR signaling pathway." (PMID 29670510, 2018). "Vandetanib induces autophagy by inhibiting the PI3K/AKT/mTOR pathway, whereas pharmacologic (chloroquine and 3-MA) or genetic (Beclin-1 and ATG7 knockdown) autophagy inhibition boosts the antineoplastic effect of vandetanib through apoptosis by the mitochondrial pathway in glioma cell lines." (PMID 30486451, 2018). "Additionally, our immunohistochemistry results suggest that metabolic and mTOR activity alterations are not related to the recent glioma classification, and these protein expression profiles show individual differences in patients’ materials." (PMID 30574020, 2018).
glioma (continued). "MAPK signaling is commonly activated in pediatric low grade gliomas through BRAF fusions suggesting this rather than PI3K signaling may commonly activate mTOR signaling in these tumors." (PMID 27926496, 2017). "Targeted therapies with mTOR kinase inhibitors have not proven to be effective in glioma therapy." (PMID 27752843, 2017). "Moreover, we demonstrated that the possible mechanism of the si-UBE2C-induced inhibition of glioma cell proliferation might be autophagic cell death induction and PI3K-Akt-mTOR signaling pathway inactivation." (PMID 28767320, 2017). "The increased level of miR‐497 in TMZ‐resistant glioma cells was concurrent with the up‐regulation of insulin‐like growth factor 1 receptor (IGF1R)/insulin receptor substrate 1 (IRS1) pathway‐related proteins, that is, IGF1R, IRS1, mammalian target of rapamycin (mTOR), and Bcl‐2." (PMID 28064447, 2017). "Furthermore, administration of DS enhanced the antitumor efficacy of temozolomide against GBM in U87 glioma models, which shows that PI3K/mTOR inhibitors may enhance alkylating agent-mediated cytotoxicity, providing a novel regimen for the treatment of GBM." (PMID 28423515, 2017). "Progesterone dependent PI3K/Akt/mTOR signaling modulation was observed in glioma cells in vitro although the nPGR was blocked by RU486, an inhibitor of the nPGR, suggesting that the nongenomic action of progesterone via MAPRs has an important role in the progesterone responsiveness of glioma cells." (PMID 27340667, 2016). "The results demonstrated that HuR is activated through the PI3K/AKT/mTOR pathway in both GSCs and non-GSCs glioma cells, which suggested that elevation of HuR levels in GSCs compared to non-GSCs glioma cells might be not due to transcriptional regulation." (PMID 27166258, 2016). "Furthermore, although not yet investigated in TC, PI3k/Akt/mTOR inhibitors can be combined with autophagy regulators: the PI3K–mTOR inhibitor NVP-BEZ235 synergized with chloroquine to induce apoptosis in glioma xenografts." (PMID 25741318, 2015). "So far, mTOR-targeted therapies are not in clinical use for first line therapy in glioma patients, nevertheless in case of tumor relapse or progression mTOR-targeted therapy regimens might become important therapeutic options." (PMID 25993328, 2015). "Given the prevalence of activation of the PI3K/mTOR axis and BRAF V600E mutations in pediatric tumors, we designed a pre-clinical study to determine whether inhibitors of mTOR and of BRAF V600E cooperate to enhance cytotoxicity specifically in pediatric low-grade gliomas." (PMID 23717811, 2013). "Interestingly, the overexpression of SSAT down-regulated AKT and mTOR expression in glioblastoma cells suggesting an effect on cell survival, since the DENSPM-inducing AKT and mTOR down-regulation has been proven to lead glioma cells to apoptosis." (PMID 22179681, 2012). "In conclusion, hirudin can induce autophagy‐dependent cell growth arrest through mTOR inactivation in glioma cells, but not apoptosis, which provides new insights into the molecular antitumor mechanism of hirudin and provides a promising strategy for the treatment of glioma patients." (PMID 37539490, 2023). "However, when combined with temozolomide, an alkylating agent, NVP-BEZ235 has been shown to downregulate PI3K/mTOR pathways, in glioma cells but in combination with AZD6244, a MAP kinase inhibitor, NVP-BEZ235 significantly reduced radio-sensitization of irradiated lung cancer and glioma cells." (PMID 36172166, 2022). "In addition, experiments in glioma mouse model unveiled that GBM-exo could activate PI3K/AKT/mTOR signaling pathway, validated by the increased expression levels of p-PI3K/PI3K, p-AKT/AKT and p-mTOR/mTOR." (PMID 33663509, 2021).